RNU6-339P (RNA, U6 small nuclear 339, pseudogene)
Gene: Small nuclear RNA gene on chromosome 15 (84,938,416 to 84,938,522, reverse strand). Ensembl gene ENSG00000207037.
Homologues: Orthologues: chimpanzee U6 (100% identical), macaque U6 (93% identical), pig U6 (81% identical), pig U6 (80% identical), guinea pig U6 (69% identical). Paralogues in human: RNU6-41P (90% identical), RNU6-44P (90% identical), RNU6-10P (88% identical), RNU6-1145P (88% identical), RNU6-12P (88% identical), RNU6-13P (88% identical), RNU6-166P (88% identical), RNU6-25P (88% identical), RNU6-29P (88% identical), RNU6-32P (88% identical), RNU6-38P (88% identical), RNU6-639P (88% identical), and 1288 more.